TRMT11 (tRNA methyltransferase 11)
Description:
Catalytic subunit of the TRMT11-TRM112 methyltransferase complex, that specifically mediates the S-adenosyl-L-methionine-dependent N(2)-methylation of guanosine nucleotide at position 10 (m2G10) in tRNAs. This is one of the major tRNA (guanine-N(2))-methyltransferases.
Synonyms: C6orf75; MDS024; dJ187J11.2; TRM11; TRMT11-1
Tractability: PROTAC: ubiquitination databases record sites on it.
Gene: Protein-coding gene on chromosome 6 (125,986,428 to 126,203,817, forward strand). Ensembl gene ENSG00000066651.
Subcellular location: Cytoplasm
Subcellular location (Human Protein Atlas): Nuclear bodies
Pathways (Reactome):
Metabolism of RNA: tRNA modification in the nucleus and cytosol
Gene Ontology:
Molecular function: protein binding; tRNA (guanine(10)-N2)-methyltransferase activity; methyltransferase activity; nucleic acid binding; S-adenosylmethionine-dependent methyltransferase activity
Biological process: RNA methylation
Cellular component: cytoplasm; methyltransferase complex; mitochondrion; tRNA (m2G10) methyltransferase complex; tRNA methyltransferase complex
Genetic constraint (gnomAD): Loss-of-function variants: 30 observed, 37.73 expected, observed/expected ratio (o/e) 0.8, 90% interval 0.59 to 1.08. The upper end of that interval is the gene's LOEUF score, 1.08, which puts it in group 4 of 6, group 1 being the genes least tolerant of losing a copy. Missense variants: 371 observed, 386.61 expected, observed/expected ratio (o/e) 0.96, 90% interval 0.88 to 1.05. Synonymous variants: 124 observed, 138.85 expected, observed/expected ratio (o/e) 0.89, 90% interval 0.77 to 1.04.
Homologues: Orthologues: chimpanzee TRMT11 (99% identical), macaque TRMT11 (98% identical), pig TRMT11 (94% identical), dog TRMT11 (93% identical), mouse Trmt11 (92% identical), guinea pig TRMT11 (91% identical), rabbit TRMT11 (91% identical), rat Trmt11 (86% identical), tropical clawed frog trmt11 (70% identical), zebrafish trmt11 (69% identical), Drosophila melanogaster CG1074 (41% identical), Caenorhabditis elegans Y71F9AL.1 (34% identical).
Diseases named in the same sentence as TRMT11 in open-access papers:
TRMT11 is named in the same sentence as 8 diseases in open-access papers, as found by Europe PMC text mining. Sharing a sentence is not in itself a finding about the gene and the disease. The quoted sentences say what the papers report.
glioma (1 paper, 2024). A benign or malignant brain and spinal cord tumor that arises from glial cells (astrocytes, oligodendrocytes, ependymal cells). "Results revealed that TRMT2B, TRMT11, METTL8, TRMT6, and TRUB2 were upregulated in glioma, while METTL6 was downregulated." (PMID 38824202, 2024).
heart failure (1 paper, 2025). Inability of the heart to pump blood at an adequate rate to meet tissue metabolic requirements. "This study preliminarily analyzed the association between TRMT11 and NMN in heart failure, adding a new perspective to the in-depth understanding of the molecular mechanisms of this disease and the exploration of potential therapeutic strategies." (PMID 41477636, 2025).
lupus nephritis (1 paper, 2024). Glomerulonephritis in the context of systemic lupus erythematosus. "Additionally, cg08399134 is within TRMT11, transfer RNA methyltransferase, which has been shown to selectively enhance protein translation to drive T-cell proliferation in vivo when methylated and is associated with lupus nephritis." (PMID 39696438, 2024).
cancer (6 papers, 2019 to 2024). A tumor composed of atypical neoplastic, often pleomorphic cells that invade other tissues. "The functional significance of TRMT11/THUMPD2/THUMPD3-mediated tRNA m2G modifications in cancer cells remains largely unexplored compared to extensively investigated modifications such as m7G and m5C." (PMID 39019857, 2024). "Therefore, further validation is required to ascertain the involvement of TRMT112 and TRMT11/THUMPD2/THUMPD3 in the proliferation of diverse cancer cells." (PMID 39019857, 2024). "The deletion of TRMT11 reduces the stability of tRNA and may therefore adversely impact the protein translation of cancer cells, while the loss of GRIK2 may promote the growth of cancer cells." (PMID 31164957, 2019). "Human TRMT11 is involved in carcinogenesis as part of a fusion gene with GRIK2, which is found in many cancer types." (PMID 34948388, 2021). "However, limited studies have examined the effect of TRMT2B, TRMT11, and TRUB2 in cancers." (PMID 38824202, 2024). "However, the concomitant absence of both THUMPD3 and TRMT11 results in an almost complete loss of m2G in tRNAs and strongly affects the proliferation of the HCT116 cancer cell line." (PMID 37283053, 2023). "The absence of TRMT11 may produce less efficient and unstable translation of mRNA into protein in cancer cells due to tRNA defects." (PMID 30705370, 2019).
tumor (3 papers, 2019 to 2025). "Additionally, METTL6 and TRMT11 encode tRNA methyltransferases that regulate transcript processing and promote tumor cell proliferation." (PMID 40561176, 2025). "Interestingly, TRMT11 gene fusion with GRIK2 (TRMT11-GRIK2) has been identified as a frequent event in several tumor types, including primary and lymph node metastatic cancer from breast, colon, and ovary." (PMID 37369946, 2023). "A more dramatic loss of function is identified in the TRMT11-GRIK2 gene fusion; the TRMT11-GRIK2 gene fusion eliminates the open-reading frame of GRIK2, which is a potential tumor suppressor, and produces a large truncation of TRMT11, which is a tRNA methyltransferase." (PMID 31164957, 2019). "Consequently, lack of TRMT11 may produce less efficient and unstable translation due to tRNA defects, or protein translation repression; plus the loss of GRIK2 tumor suppressor activity." (PMID 37369946, 2023).
TRMT11 also shares sentences with these, for which no sentence is quoted: autism (1 paper); colon cancer (1); prostate carcinoma (1).